MPO (myeloperoxidase)
Diseases named in the same sentence as MPO in open-access papers (continued):
Sharing a sentence is not in itself a finding about the gene and the disease.
colitis (continued). "These anti-inflammatory and antioxidant effects have been similarly reported in various pathological models, including colitis, ischemia–reperfusion injury, and diabetes, where MB administration reduced TNF-α, IL-1β, IL-6, and CRP levels, suppressed MPO and MDA, and enhanced SOD activity." (PMID 40870501, 2025). "Mice lacking PAR2 were protected from symptoms of experimental colitis induced by 2,4,6‐trinitrobenzene sulfonic acid (TNBS), with reduced weight loss, myeloperoxidase (MPO) activity, colon thickening, and microscopic damage compared to wild‐type mice." (PMID 39392222, 2025). "In colitis models, (–)-fenchone (150 mg/kg) elevated GSH and SOD while reducing MDA and MPO levels." (PMID 41305003, 2025). "In a mouse model of colitis induced by dextran sulfate sodium, BUD was found to inhibit the expression of cytokines (e.g., myeloperoxidase/MPO and tumor necrosis factor/TNF-α) and inflammatory enzymes (e.g., cyclooxygenase-2/COX-2 and inducible nitric oxide synthase/iNOS)." (PMID 40284499, 2025). "In a murine model of acetic acid-induced colitis, pregabalin reduced both macroscopic and microscopic intestinal damage and inflammation, decreasing colonic levels of TNF-α, IL-6, IL-1β, and myeloperoxidase (MPO) activity [DOI: 10.4103/1735-5362.329924]." (PMID 40650291, 2025). "Within the trio of phases, the colonic impairment in mice with colitis reached its peak during the acute stage, as evidenced by alterations in body weight change, disease activity index (DAI) score, myeloperoxidase (MPO) activity, intestinal permeability, and colon length." (PMID 40947937, 2025). "The NPs-treated mice showed no weight loss and had substantial preservation of colon length compared to the non-treated group, whilst colonic myeloperoxidase activity was at the same level as the control (non-colitis-induced) group." (PMID 40699810, 2025). "APA exhibited strong antioxidant activity and significantly attenuated colitis severity, as evidenced by reduced Disease Activity Index (DAI) scores, decreased colon inflammation, suppression of Myeloperoxidase (MPO)-mediated neutrophil infiltration, and modulation of redox biomarkers." (PMID 41020900, 2025). "In the circumstance of DSS-induced colitis, we found iron supplementation resulted in more infiltration of inflammatory cells (e.g., CD3+ T cells and MPO+ neutrophils), and it also changed the morphology of CX3CR1+ resident macrophages surrounding intestinal crypts." (PMID 40416374, 2025). "Histological scoring of the inflamed tissue supported the observation that IPA treatment improved chronic colitis in WT mice but had no impact on colitis in the MPO-KO mice." (PMID 39133648, 2024). "As expected, high levels of MPO activity or gene expression were observed in mice with DSS-induced UC, which was similar to the findings of a previous study that showed that MPO activity was dramatically upregulated in rats with acetic acid-induced colitis." (PMID 39161963, 2024). "While pharmacological MPO inhibition mitigates all indices of experimental colitis, no studies have corroborated the role of MPO using knockout (KO) models." (PMID 38673843, 2024). "A mouse model of colitis showed a poor response to epithelial damage in the absence of SEMA4D maintaining myeloperoxidase activity, suggesting a selective defect in the response of infiltrating lymphocytes." (PMID 39596507, 2024). "Treatment with 60 mg/kg of CBD, but not lower doses, significantly reduced colitis symptoms, such as inflammation, cytokine levels, and MPO activity, while also normalizing glucagon-like peptide-1 (GLP-1) levels." (PMID 39682761, 2024). "Our study attempted to delineate the role of MPO during experimental colitis via the MPO gene deletion approach, as opposed to our previous attempts using pharmacological interventions." (PMID 38673843, 2024).
colitis (continued). "MPO, indicative of neutrophil infiltration, was notably decreased in HD-treated groups (6 and 12 mg/kg), along with a reduction in peripheral blood WBC counts in colitis mice, signifying mitigated inflammation (P < 0.05, vs. model)." (PMID 39650157, 2024). "This may explain the dichotomy observed in this study when compared to our previous studies of pharmacological inhibition of MPO and improved clinical outcomes in DSS-induced colitis." (PMID 38673843, 2024). "Furthermore, the treatments normalized spleen to body weight ratios, splenic MPO activity, and GLP-1 levels, indicating the mitigation of extraintestinal manifestations of colitis." (PMID 39682761, 2024). "Using an acute and chronic model of DSS colitis, we observed a progressive decrease in disease severity in mice lacking MPO." (PMID 39133648, 2024). "In a rat model of AA-induced colitis, phloretin, administered orally either before or after induction of colitis (50 mg/kg), effectively reduced plasma ALP and LDH levels, inflammatory markers (MPO, NO, eosinophil peroxidase), and colon ICAM-1 gene expression." (PMID 39494333, 2024). "Moreover, CMP I can also regulate the expressions of the MPO enzyme and SOD enzyme in mouse sera to prevent the peroxidation of colon tissue, thus reducing the symptoms of colitis in mice." (PMID 37240380, 2023). "MPO, an important sign of neutrophile granulocytes infiltration, was increased in DSS-induced colitis mice while restored by S. boulardii treatment in our study, indicating that S. boulardii prevented granulocyte recruitment and inflammatory cells infiltration induced by DSS." (PMID 37492256, 2023). "However, treatment with RG or fRG suppressed UCDF-induced myeloperoxidase, TNF-α, and IL-6 expression, and NF-κB+CD11c+ cell number, leading to the amelioration of colitis." (PMID 36926604, 2023). "Furthermore, our results support that Ononin reduces ALP and MPO production and enhanced GSH levels in DSS‐induced colitis mice." (PMID 36840499, 2023). "Embelin-loaded enteric-coated microspheres can significantly reduce the ulcer activity score, oxidative stress level (downregulate the expression of MPO, MDA, LPO), upregulate the level of glutathione, and reduce the inflammatory reaction in acetic acid-induced colitis rats." (PMID 37033644, 2023). "In a murine model of colitis, the previous and during-induction administration of CC-AST relieves colitis and significantly inhibits the expression of the inflammatory markers IL-1β, IL-6, TNF-α, cyclooxygenase-2, myeloperoxidase (MPO), iNOS, and NO in a more potent way than free AST." (PMID 37514016, 2023). "Treatment with VAS2870 ameliorated DSS-induced colitis with a reduction in DAI, MPO levels, macroscopic and histological scores, secretion of proinflammatory cytokines (TNF-α, IL-6, and IL-1β), and an increase in colon length, which were not affected by SS treatment." (PMID 37239114, 2023). "Furthermore, PELNs demonstrated the ability to suppress the expression of pro-inflammatory cytokines (IL-6, IL-12, IL-1β, and TNF-α) and MPO, and increase the levels of the anti-inflammatory cytokine IL-10, thereby alleviating DSS-induced colitis in mice." (PMID 37653406, 2023). "In addition, the levels of oxidative stress (MPO, SOD, and MDA) and inflammatory cytokines (TNF-α, IL-1β, IL-6, and IL-10) were reversed by PHI in colitis mice." (PMID 36768559, 2023). "The results showed that compared with the control group, the number of Ly6G‐positive cells and the content of NETs, as shown by coincident staining for citrullinated histone H3 (CitH3) and MPO, markedly increased in the venous thrombus of the mice with the DSS‐induced colitis." (PMID 37590310, 2023). "Similarly, when an extract of blueberry anthocyanins (BBA) was used, disease activity, MPO and MDA levels were reduced in murine colitis." (PMID 37701897, 2023).
colitis (continued). "Consistently with the data obtained in murine colitis, Ade/HA determined a significant decrease in the release of IL-1β, TNF-α, IL-6, MPO, and MDA accumulation in cytomix-stimulated tissues, and these effects were accompanied by a significant reduction in the expression of HYAL-1." (PMID 38203336, 2023). "The semiquantitative immunohistochemistry data suggested that MPO expression was significantly elevated in mice treated with DSS compared to that in control mice, while treatment with Fp-EVs suppressed the elevation of MPO activity in DSS-induced colitis mice." (PMID 37968625, 2023). "The activity of MPO was detectable in the noncolitis control (32.50 ± 2.5 mU/mg protein) but was significantly (p < .0001) increased in the colitis control with mean level of 165.0 ± 6.45 mU/mg." (PMID 37249276, 2023). "The administration of TRPV4-selective and non-selective antagonists in a mouse model of colitis significantly reduced macroscopic damage, myeloperoxidase activity, and pain reduction; conversely, TRPV4 agonist treatment yielded opposite results." (PMID 37808188, 2023). "Previously, administration of dietary quercetin or a combination comprising quercetin and quercetin monoglycoside restored reduced body weight and enhanced oxidative stress mediators including malonaldehyde myeloperoxidase and GSH in a 3% DSS-induced colitis model." (PMID 35884960, 2022). "In a rat model of colitis, EVs from BM-MSC reduce oxidative perturbations increasing antioxidant enzymes (SOD and GSH) and decreasing in the activity of malondialdehyde (MDA) and MPO." (PMID 36012170, 2022). "Compared to the control group, clodronate liposome administration reduced the MPO activity and DAI of colitis but not the weight loss or colon length, while injection of the anti-CD20 monoclonal antibody had little effect on colitis." (PMID 35371051, 2022). "Previous studies have proved that a variety of electrophilic compounds can alleviate colitis in terms of disease activity index (DAI) scores, histopathological analysis and MPO activity, including curcumin, xanthohumol, cinnamaldehyde (CA), SFN, ISO, and caffeic acid phenethyl ester." (PMID 36552614, 2022). "In one study, SAMP1/YitFc mice administered with Splenda did not aggravate colitis but increased the level of myeloperoxidase (MPO) in colon tissue." (PMID 35893902, 2022). "Oral administration of RSL seed water extract suppressed intestinal inflammatory damages in both animal models, decreasing the MPO activity and the secretion of TNF-α and IL-1β, inhibiting also malondialdehyde production and glutathione reduction in the colon of colitis rats." (PMID 36615689, 2022). "The MPO activity was elevated >5-fold by DSS in C57BL/6 WT mouse colon, but by only 2-fold in Mmp7-/- mouse colon, compared to the respective controls, suggesting that MMP-7 knockout protected against colitis." (PMID 36275703, 2022). "MPO activity and inflammatory mediator levels were elevated by DNBS-induced colonic inflammation." (PMID 36678670, 2022). "In addition, FREG regulated the tight junction proteins, and markedly decreased TNF-α, MPO levels and significantly increased the secretory IgA levels in TNBS induced colitis rats." (PMID 35130890, 2022). "Moreover, since neutrophil-myeloperoxidase (MPO) is an abundant granule enzyme that catalyzes the production of ROS in UC, we found a notable increase in MPO activity in DNBS-induced colitis mice when compared to the control mice." (PMID 35893393, 2022). "Chlorogenic acid can downregulate MPO expression levels by inhibiting TLR4-mediated PI3K/Akt and NF-κB pathways, reducing NEUT infiltration and expression of pro-inflammatory cytokines in DSS-induced colitis as well as LPS-stimulated RAW 264.7 cells." (PMID 35873579, 2022). "The MPO activity was significantly increased in the TNBS colitis group (117.45 ± 8.5091 pg/mL) compared to the non-colitis (17.1 ± 0.9483 pg/mg of tissue) and BEY-treated groups (61.4 ± 8.087 pg/mg of tissue)." (PMID 35565934, 2022).
colitis (continued). "MPO levels are elevated in IBD, and MPO inhibition in animal models of colitis is protective." (PMID 36293108, 2022). "Current findings indicated that the administration of 400 mg/kg Aloe vera extract rectally on experimental colitis in rats can significantly attenuate the increased levels of TNF-a, IL-6, NO, MPO, and MPA and reduce the inflammations as compared to the TNBS-induced colitis model." (PMID 34912469, 2021). "Regarding colonic MPO and MDA, pairwise comparison revealed that all treatment groups except low-dose 6-paradol (50 mg/kg) significantly reversed the changes in these parameters compared to the untreated colitis group." (PMID 33441125, 2021). "However, oral gavage of NK210 and/or NK219 suppressed cyclophosphamide-induced colitis: they increased IFN-γ, TNF-α, and IL-10 expression, but decreased myeloperoxidase activity and IFN-γ to IL-10 and TNF-α to IL-10 expression ratios in the colon." (PMID 34667205, 2021). "Additionally, all the groups differed significantly in measurements of colonic GSH, colonic MPO, and colonic MDA (p < 0.001) compared to the untreated acetic acid-induced colitis group." (PMID 33441125, 2021). "Oral administration of NK210 and/or NK219 did not affect colitis-related colon shortening, myeloperoxidase activity, and TNF-α and IL-10 expression in the colon." (PMID 34667205, 2021). "Importantly, in rats with trinitrobenzenesulfonic acid (TNBS)-induced colitis, GALR agonism with galanin ameliorated the extent and severity of the colonic injury and reduced myeloperoxidase (MPO) activity, TNFα levels and nitric oxide production." (PMID 33436730, 2021). "Although the reduction of MPO expression by Q and the I3C metabolite DIM has already been reported in another mouse model of DSS colitis, in the present work, we could demonstrate that these effects were AhR-dependent." (PMID 33668818, 2021). "The severity of induced colitis in PleΔIEC mice coincided with larger inflamed areas at days 4 and 6 after the initiation of DSS-treatment, corresponding to a higher influx of MPO-positive neutrophils and intestinal epithelial injury." (PMID 33674761, 2021). "However, treatment with C29, DW2009, or donepezil reduced LPS-induced colon shortening, myeloperoxidase activity, and TNF-α and IL-1β expression and increased IL-10 expression in the colon, leading to in the alleviation of colitis." (PMID 34579150, 2021). "In addition, LP-YS4 significantly increased the activities of GSH and SOD while decreasing those of MPO and MDA in the colon tissue of colitis mice (P < 0.05)." (PMID 32849906, 2020). "Medium and high dose bilobalide markedly reduced the inflammation of colitis proved via elevation of bodyweight, decrement in disease activity index (DAI), alleviation of colon damage as well as reduction in activity of colon tissue myeloperoxidase activity." (PMID 32670051, 2020). "More specifically, treatment with LP-YS4-H significantly increased the levels of (8.05 ± 0.35 μmol/mg) and SOD (22.69 ± 1.98 μmol/gprot) in colon tissue and markedly decreased those of MPO (10.98 ± 1.05 mU/mg) and MDA (0.51 ± 0.09 nmol/mg) when compared to colitis model group." (PMID 32849906, 2020). "Our findings also indicated that colitis could lead to decrease in GSH and SOD levels as well as increase in MDA and MPO levels." (PMID 32849906, 2020). "Treatment with CloA did not change MPO activity in the intestines of mice with colitis possibly because MPO activity mainly reflects the function of neutrophil cells, not macrophages." (PMID 33117347, 2020). "Soybean-derived dipeptides and tripeptides decreased the colonic expressions of proinflammatory IFNG, IL-1B, IL-12B, TNF, and IL-17A and MPO activity and increased Foxp3 expression and CD4+CD25+ T cells; therefore, the colon and ileum inflammation of piglets with DSS-induced colitis was attenuated." (PMID 32963495, 2020).
colitis (continued). "Indeed, in vivo NAC treatment successfully ameliorated acetic acid-induced colitis by reversing pro-inflammatory mediators TNF-α, IL-6, and MPO in rats." (PMID 33224136, 2020). "Intraperitoneal administration of 5-HT significantly increases the expression of interleukin (IL)-1β and IL-6 and the activity of myeloperoxidase (MPO) by activating 5-HT3 and 5-HT4 receptors in colonic mucosa of colitis mice, while blocking the signal can reduce the pain." (PMID 32117308, 2020). "In addition, GW9662 markedly weakened the anti-colitis effect of MA as evidenced by higher DAI, shorter colon length, higher MPO activity, and more serious pathological lesion in the colon tissues." (PMID 32929062, 2020). "Vagotomy did not affect Escherichia coli-induced colitis, as it did not inhibit Escherichia coli-induced myeloperoxidase activity, IL-1β expression, and NF-κB+/Iba1+ cell counts in the colon." (PMID 32669127, 2020). "Moreover, significant effects on colon weight, myeloperoxidase (MPO) activity, histopathology scores and colon morphology scores were seen in an acute TNBS colitis model in rats after oral treatment with 600 mg/kg/day." (PMID 32545207, 2020). "Similarly, α-LA also reduced MPO levels in LPS-induced lung injury and trinitrobenzene sulfonic acid (TNBS)-induced colitis." (PMID 33152996, 2020). "The level of total cyclooxygenase (COX), prostaglandin E2 (PGE2), tromboksan A2 (TXA2), and myeloperoxidase (MPO) in the colon significantly increased in animals with induced colitis without supplementation (CβG− vs. HβG−)." (PMID 31590413, 2019). "In trinitrobenzene sulfonic acid (TNBS)-induced colitis, perinatal exposure of dietary bisphenol A increased myeloperoxidase activity in female rats but not in male rats." (PMID 31109097, 2019). "In addition, KM1608 inhibited MPO activity and pro-inflammatory cytokines in the colon tissue lysate of DSS-induced colitis." (PMID 30696085, 2019). "On the other hand, the measurements of MPO levels demonstrated that the animals with colitis and treated BmooMP-alpha-I were not statistically significant compared to the untreated DSS-induced colitis group." (PMID 31467484, 2019). "Although these experiments were conducted in a mouse model of DSS-induced colitis, CGA could similarly inhibit the release of proinflammatory cytokines, such as MPO and TNF-α, in ulcerative colitis." (PMID 30971953, 2019). "MfB and MfB-G mice groups had very similar MPO values with respect to the control, suggesting that both beverages apparently do not trigger an inflammatory response in the colon in the absence of colitis." (PMID 30987294, 2019). "In C57BL/6 mice, β-sitosterol (20 mg/kg/day) administration for 56 days prevented the colon shortening (~8%) and reduced MPO activity in colon tissue (~35%), what led to a lower level of pro-inflammatory cytokines (IL-1β, TNF-α and IL-6) after colitis induction by high fat diet (60 Kcal% from fat)." (PMID 30987294, 2019). "In addition, ALA significantly reduced the expression of pro-inflammatory genes, the activity of MPO, and the production of TNF-α, IL-6, NO and PGE2 in DSS colitis mice." (PMID 31719637, 2019). "MPO activity and histology scores were also increased markedly by DSS treatment compared with that in the Con group (p < 0.05); however, Fro, Cp, and Cs ameliorated these effects in the DSS-induced colitis model (p < 0.05)." (PMID 30211217, 2018). "While systemic and topical DPP-4 inhibitors reduce colitis severity and promote healing of colitis, Dpp4 KO does not protect from colitis but increases colonic myeloperoxidase activity and nuclear factor κbp65 subunit and modifies leucocyte trafficking." (PMID 30186247, 2018). "In the present study, the LC27 and LC67 mixture PM, synergistically rather than additively, attenuated TNBS-induced colitis such as colon shortening, myeloperoxidase activity, TNF-α and IL-10 expression, and Th17 and Treg cell differentiation." (PMID 29760423, 2018).